CD4 (CD4 molecule)
Diseases named in the same sentence as CD4 in open-access papers (continued):
Sharing a sentence is not in itself a finding about the gene and the disease.
infection (continued). "Cervical epithelial cells do not possess the receptors such as CD4+ and CXCR4/CCR5 for HIV-1 entry, and hence these cells are not susceptible for direct infection." (PMID 34835072, 2021). "We investigated the role of IL-21, a CD4+ T follicular helper cell (Tfh) regulator, on flu vaccine antibody response in nonhuman primates (NHPs) in the context of age and controlled SIV mac239 infection." (PMID 34491910, 2021). "Here, the expression of iNOS and CNS inflammation is largely enhanced by the adoptive transfer of immune CD4+ T cells but not CD8+ T cells relatively late in the infection, although the bacteria were efficiently eliminated by both cell populations." (PMID 34452021, 2021). "2W1S-specific CD4+ T cells were found to expand in the lung parenchyma of infected mice 14 days post-infection, whereas this did not occur in mice infected with the parental strain or in naïve controls." (PMID 34237106, 2021). "It was suggested that the enhanced infectivity of neutrophil-bound virus was not due to stimulatory signals provided, or by either infection of the cells or via selection of infectious particles, as observed in another CD4-negative cell type, the Raji cells." (PMID 33777022, 2021). "Although this likely results from HIV preferentially targeting memory CD4+ T cells over naive ones, theoretically, it could also result from upregulation of CD45RO on naive cells after infection." (PMID 33910003, 2021). "In the absence of TGF-β signaling, virus-specific CD8+ T cells had reduced levels of the pro-apoptotic molecule Bcl-2-like protein 11 (Bim), which correlated with increased survival and functionality of both virus-specific CD4+ and CD8+ T cells during infection." (PMID 34696381, 2021). "Our results showed that viral titer in brains was comparable in both mouse strains at the acute phase of infection when CD4+ T cell function is not critical, as explained in the current study as well as previous studies." (PMID 34898656, 2021). "Both in terms of the percentage of Cyt+ CD4 T cells in the GT, and in the Th1 or Th17 cytokine subset pattern, and regarding the local humoral response, the SC and SIM animals looked similar following a second infection." (PMID 34925371, 2021). "Importantly, lung tissue analysis in the diabetic mice showed a decreased number of macrophages, CD4+ T-cells, and lower expression of TNFα and IL-6 in the HFD group, compared to control DPP4H/M mice following infection." (PMID 33692997, 2021). "Infection with SARS-CoV-2 drastically impacts the immune system via induction of an inflammatory storm, an increase in neutrophil count as well a decrease in lymphocyte count, specifically CD4+ and CD8+ T cells." (PMID 34036149, 2021). "Furthermore, in humans, LASV-specific CD4+ and CD8+ T-cell responses are activated early during infection and continue to be detected after recovery despite low (or absent) antibody responses." (PMID 33654106, 2021). "We have previously shown that early post-infection CD4 T-cell counts are able to predict CD4 T-cell recovery independent of CD4 nadir." (PMID 34449812, 2021). "On day 4 post-pH1N1 virus challenge infection, significantly higher percentages of nucleoprotein (NP)-specific effector T cells (both CD3+CD4+IFN-γ+ and CD3+CD8+IFN-γ+) were observed in Prime-IIV-IIV and B-cH9/1 virus (Prime-only) immunized PBMCs as compared to those from naïve ferrets." (PMID 33440898, 2021). "HIV-1 establishes a stably integrated, non-productive latent state of infection of individual cells, mainly long lived CD4+ T cells that are maintained by homeostatic proliferation." (PMID 34834213, 2021). "Three days post infection CD8+ T cells demonstrated increased proliferation in mice infected with rVV NY-ESO-1 C165V compared with CD4+ T cells, while no proliferation was noted in uninfected mice or irrelevantly infected mice with rVV SIINFEKL." (PMID 34088742, 2021).
infection (continued). "We pre‐treated primary CD4+ T cells isolated from peripheral blood mononuclear cells (PBMCs) of three human donors with Vs (25 ng/μl), infected with HIV‐1 NL4.3, and measured p24 HIV capsid protein in the supernatant at 3‐ and 5‐day post‐infection." (PMID 33793064, 2021). "Furthermore, we have previously shown suppression of both CD4+ and CD8+ T cell responses in ponies on day 7 post-infection with EHV-1." (PMID 33430330, 2021). "In addition to acting as HIV-1 viral reservoirs, infected macrophages can transmit HIV-1 to T CD4/CD8 cells through cell-to-cell contact, leading to a 10-fold higher rate of infection than free cell virus." (PMID 34445073, 2021). "In brief, RNH1 is upregulated at the early stage of infection but downregulated after 2 weeks when comparing its expression in infected CD4+ T cells to non-infected ones." (PMID 34781942, 2021). "In order to consolidate the link between IL-17, produced primarily by B. pertussis-specific CD4 TRM cells in the nasal cavity, and Siglec-F+ neutrophils and bacterial clearance, we depleted neutrophils in Il17A−/− mice during primary infection with B. pertussis." (PMID 33976385, 2021). "However, the authors infected activated CD4+ T cells from HIV-1–negative donors, amplified 22 independent HIV-1 proviruses after a single round of infection, and showed that 59% were intact." (PMID 33784259, 2021). "Based on our findings, we hypothesized that the infection of CMV incites extensive memory inflation and a specific differentiation course of CD4+ T cells: first, CD27- effector memory CD4+ T cells that express adhesion molecule CD11a (T-3) are expanded." (PMID 33936035, 2021). "Mice, which have been infected once but not reinfected, served as a control group for the secondary infection and exhibited reduced Trm17 responses in terms of IL-17A production and overall CD4+ T cell frequencies." (PMID 33595670, 2021). "Although adult B. malayi antigens can influence HIV-1 trans-infection of CD4+ T cells, they have no deleterious impact on dendritic cell-derived T helper cytokine profiles against the virus." (PMID 34603287, 2021). "As CD4 is important for HIV entry and infection, this could also contribute to the increased infection rates by CCR5-tropic HIV seen for T-PBMCs." (PMID 34899645, 2021). "Mice lacking CD4+ T cells due to deficiency in recombinase activating gene (RAG), TCR β chain, CD4, or MHC class II succumb to infections with mycobacteria." (PMID 34943793, 2021). "Concomitantly, IL-33 inhibits the differentiation of IL-17A-producing CD4+ T cells, which have the potential to reverse the negative effect of IL-33 during infection." (PMID 33654214, 2021). "The lack of infection of H7 cells with CCR5 tropic HIV confirms CCR5 KO as they expressed the HIV receptor CD4 and the co-receptor CXCR4 comparable to WT TZM Cells." (PMID 33516234, 2021). "It is associated with T-cell tolerance and is upregulated in CD4+ T-cells in the acute phase of infection, which may be related to a significant increase in inhibitory receptors (such as PD-1 and CTLA-4) expressed by CD4+ T-cells." (PMID 34943817, 2021). "Most tissues harbour CD4+ T cells, although the contribution of each tissue to the whole‐body HIV reservoir size varies due to tissue‐specific differences in the numbers, phenotypes and infection frequencies of CD4+ T cells and other infectable cells." (PMID 34235864, 2021). "CD8+ cytotoxic T-cells and CD4+ Th1 cells fight intracellular microbes by killing infected cells, releasing pro-inflammatory and anti-viral cytokines (IFN-γ), and recruiting phagocytes to the infection site." (PMID 35058937, 2021). "However, previous studies on influenza-specific T cells demonstrated that pre-existing memory CD4+ and CD8+ lymphocytes were able to provide protection against subsequent infections." (PMID 34067349, 2021).
infection (continued). "This suggests that, although macrophages do not release virus as robustly as CD4+ T cells, they are still capable of re-establishing infection after ART interruption." (PMID 34451482, 2021). "Stimulation with CD8 T or naïve CD4 T cells however, did no show any effect on the bacillary counts of ΔhisD 48 h post infection." (PMID 33767335, 2021). "In the DC-mediated trans infection cocultures, we could detect HIV-1 p24 only in the DC-total CD4+ T cell wells, with very low levels in the DC-TN cocultures." (PMID 33688006, 2021). "Similarly, cellular immunity seems to be crucial in the resolution of the infection, as SARS-CoV-2-specific CD4+ and CD8+ T cells circulate to some extent in recovered patients." (PMID 33936045, 2021). "In addition, compared to females, peripheral blood monocytes (PBMCs) isolated from males have greater proliferation of C. neoformans cells within them and during infection; male PBMCs had lower levels of CD3+, CD4+, and CD8+ T cells." (PMID 33808500, 2021). "While the HIV-2287 immunized animals did not appear to resist infection, their disease was attenuated with lower concentrations of infectious virus and maintenance of normal CD4 cells counts." (PMID 33914754, 2021). "CD4+ T, CD8+ T and NK cell numbers increased with infection time and peaked at 5 dpi." (PMID 34381043, 2021). "Overall, these results indicate that affinity of gp120/CD4 interactions does not vary with viral tropism and the stage of infection." (PMID 33872329, 2021). "While a relatively low fraction of CD4 T cells were characterized as TRM early after infection, a large percentage expressed TRM cell markers (CD69+CD11a+) during the encephalitic stage of infection." (PMID 34587172, 2021). "In addition to CD4 and CD8 T cells, different target cells of IL-27 have been identified in other infection models." (PMID 34045653, 2021). "Murine cells are not permissive to HTLV-1 and productive infection in humans mainly involves T-cells, particularly CD4+ T-cells." (PMID 34685494, 2021). "In both the blood and brain, CXCR3 expression on CD8+ and CD4+ T cells was up-regulated upon infection, but no detectable difference was found between WT and Pbyop1Δ parasite-infected mice." (PMID 34025654, 2021). "IFN-γ from CD4+ T cells in particular is necessary for survival, and animals lacking IFN-γ from just CD4+ T cells succumb after two months post aerosol infection; however IFN-γ’s role was mostly extrapulmonary with a limited role in the lungs." (PMID 34276708, 2021). "An optimized derivative NBD-11021 exhibited further improved antiviral activity without the enhanced infection to the CD4-/CCR5+ cells." (PMID 33922579, 2021). "Subtype D HIV-1 infections have an increased frequency of CXCR4 co-receptor usage and faster CD4+ T cell decline, which could account for the more aggressive clinical course HIV-1 subtype D infections than subtype A in sub-Saharan Africa." (PMID 33498793, 2021). "We have described one mechanism of bystander cell death that occurs in lymphoid tissue, but not in blood, involving abortive infection of neighboring resting (nonpermissive) CD4 T cells." (PMID 34418431, 2021). "According to the GO enrichment analyses, regulation of T cell activation showed high enrichment scores in the BP among the conjunctival infection group, which corresponded to the previous findings that CD4 T cells and IFN-γ play a primary role in immunity against Ct infection." (PMID 33875006, 2021). "In conclusion, this study indicates that at the initial stage of SARS-CoV-2 and SFTS infection, the blood indices of patients are distinct from each other, including WBC count, absolute LYMPH count, PLT count, absolute CD4+ T cells count, and IL-6, TNF-α, D-D, CRP and FIB levels." (PMID 34238962, 2021).
infection (continued). "We found that triggering the signaling of Dectin-2 during vaccination, augments the expansion, differentiation, and tissue residency of antigen-specific CD4+ and CD8+ T cells in the lung upon fungal and viral challenge and protects mice against experimental infection." (PMID 33735218, 2021). "b.-infected WT and cd4-/- mice suggested that either CD4 T cells played a minor role in the stimulation of these immune molecules during infection or that a compensation due to the absence of CD4 T cells occurred in the mutant mice." (PMID 34587172, 2021). "(c) For donor M, CD4+ contracting clonotypes are also identified in memory subsets 1 year before the infection, with a bias towards the CM subpopulation and a group of CD8+ clones is found in the pre-infection EM subpopulation." (PMID 33399535, 2021). "Furthermore, the Th17 cells suppress the regulatory T cells (Tregs) function through the secretion of IL-6; meanwhile, Tregs control both the CD4+ and CD8+ T cell responses after infection." (PMID 33917837, 2021). "Furthermore, CD40L-modified DCs pulsed with PC resulted in a protective antibody response in CD4-depleted mice and protected them against a PC challenge, thus indicating that immunotherapeutic approaches may represent a valid alternative to counteract PC infection." (PMID 34975811, 2021). "Interestingly, the infection rates mediated by pEVs from HCs were comparable to HIV ART-naïve pEVs, albeit lower in ART pEV-treated CD4+ T cells (HCs vs ART, p=0.02)." (PMID 34249000, 2021). "Although CD8+ T lymphocytes were not stained directly, the CD3+/CD4− T lymphocytes similarly followed the same pattern of response to infection." (PMID 34676832, 2021). "These CD4 T cells would be expected to directly contribute to virus clearance and deliver strong T helper signals to the CD8 T cells already primed during natural infection." (PMID 33923363, 2021). "All four subjects with verified infection who lacked NAbs had positive CD4+-reactivity against at least one of the peptide pools (Patients 1-4)." (PMID 34795668, 2021). "The results demonstrate an augmented percentage of IL-2+ CD4+ T cells on day four after infection compared to days 0 or 21 with or without stimulation with anti-CD3 mAb." (PMID 34869064, 2021). "Both CD4 and CD8 T cells were present in the ME and some infiltrated the Arc early after infection." (PMID 34587172, 2021). "Individuals chronically infected with HCV showed an expansion of exhausted CD8 HCV-reactive T cells but lose their HCV-reactive CD4+ T cells over time, while individuals that clear the infection do not lose their HCV-reactive CD4+ T cells." (PMID 33995373, 2021). "Although high-speed imaging of HIV-1 particles in CD4+ T cells was not possible, infection results after CPSF6 depletion and/or CsA treatment in primary PBMC largely mimicked those seen in HeLa cells." (PMID 33758083, 2021). "Proportions of liver CD4+ T cells, CD23+ B cells, SiglecF+CD11b+ eosinophils, Lin-T1/ST2+ ILC2 and F4/80+CD11b+ inflammatory macrophages were significantly reduced (p<0.05), and consistently so over the third infection & treatment cycle." (PMID 34956183, 2021). "Depletion of CD4+ T cells at a later stage after infection did not change its course, in contrast to the observed viral persistence upon CD8+ T cell depletion at this same moment." (PMID 34066322, 2021). "In parallel, in response to the infection, the increase in pro-inflammatory cytokines such as IL-6, IL-10, and IFN-γ in the lamina propria contributes to the depletion of mucosal Th17, a CD4+ T-cell population that is heavily involved in maintaining gut homeostasis." (PMID 34442651, 2021). "CD4/CD8 ratios in the SS phase were significantly increased compared with those during SE (SS vs. SE, P = 0.0017) and in the SR phase (SS vs. SR, P = 0.0128), which returned to the normal level before infection (SS vs. SN, P = 0.4280)." (PMID 34349746, 2021).
infection (continued). "Prior to infection, DP T cells showed higher TNF-α, IL-10, MIP-1β, and IL-22 expression than traditional CD4 and CD8 T cells, suggesting that these cells may potentially perform a non-specific function in the pulmonary immune response." (PMID 34929014, 2021). "The latent HIV-1 reservoir mainly resides in resting memory CD4+ T cells, but they are normally not the direct targets for infection, due to the blocks in reverse transcription, integration and host restriction by SAMHD1." (PMID 33835029, 2021). "Our data show 2W1S-specific memory CD4 T cells numerically recover by 30 days after CLP surgery, but their ability to produce effector cytokines after re-stimulation remains blunted, suggesting a potential lesion in protective capacity following re-infection." (PMID 32903436, 2020). "Previously, CD27 was analyzed as a % or MFI on IFN-γ+CD4+ T-cells of HIV+TB who were not on ART also showed good sensitivity in distinguishing active disease from infection." (PMID 32131556, 2020). "No infection was observed by either wild-type or mutants Envs in this assay, thereby ruling out CD4-independence as the mechanism through which N/CHR mutants enhance 293Trhm infection." (PMID 32098152, 2020). "Maintenance of memory CD4 T cell responses over time is a dynamic process, depending on subsequent encounters with either cognate or non-related Ag/infections that have the potential to change their phenotype and function." (PMID 32903436, 2020). "Furthermore, we demonstrated that galectin-3 facilitated HIV-1 CRF07_BC infection, which was mainly via the CRD interacting with viral gp120 and cellular CD4." (PMID 32485969, 2020). "We demonstrate that the dynamics of infection in this SHIV infant macaque model mirror those seen in HIV-1-infected children, including sustained high-level viremia and modest perturbation of peripheral CD4+ T cell frequency." (PMID 33087463, 2020). "However, since CD4+ T cells are the primary targets of HIV, efforts to make CAR4 T cells resistant to infection must be employed to ensure durable responses." (PMID 32454027, 2020). "The early induction of FoxP3+CD4+ T cells may reflect the function of TLR2-mediated signals resulting from TMEV infections." (PMID 33086489, 2020). "However, after 2 and 4 wk of infection, CSE−/− mice showed greater numbers of CD25+FoxP3− cells than WT mice in both CD4+ and CD8+ T cells." (PMID 32139610, 2020). "Here we found a detrimental increase in Cd4 / Il6 / Il10 expression in heart tissue of BALB/c mice infected with the Y strain, not observed in the absence of SLAMF1, in which Cd8 was increased at the LA phase likely allowing a better control of the infection." (PMID 32925918, 2020). "Absolute CD4 T cell counts were determined at 9 weeks post-infection (PI) in the SIV infected untreated group of animals and at 30 weeks PI in the c-ART treated group of animals and compared to their pre-infection CD4 T cells counts." (PMID 32286417, 2020). "Already at day three post infection 3.81% of all cells in the uGT were CD4 T cells, which was more than observed in nonvaccinated infected mice (1.85% of all cells)." (PMID 31993218, 2020). "We provide evidence that while infection with SM can skew the phenotype of CD4 T cells under certain conditions, it does not compromise the ability of CD4 T cells to mount a functional TH1 response to Mtb." (PMID 32117277, 2020). "Indeed, following infection with M. tuberculosis, a lower percentage of IFN-γ-producing CD4+ T cells was present in CysVac2/Advax-vaccinated lung samples compared with samples from unvaccinated animals." (PMID 33298977, 2020). "As previously reported, mDCs facilitated higher levels of productive infection in non-proliferating CD4+ T cells than pDCs (mean number of infected cells 307 and 27 EGFP+ cells/104 cells, respectively, p = 0.019)." (PMID 32109259, 2020).